NLRP8 (NLR family pyrin domain containing 8)
Description:
Involved in inflammation.
Synonyms: NALP8; NOD16; PAN4; CLR19.2
Tractability: No criterion of Open Targets' tractability assessment is met for any kind of drug.
Gene: Protein-coding gene on chromosome 19 (55,947,832 to 55,988,629, forward strand). Ensembl gene ENSG00000179709.
Subcellular location: Cytoplasm
Gene Ontology:
Biological process: regulation of inflammatory response
Cellular component: cytoplasm
Genetic constraint (gnomAD): Loss-of-function variants: 85 observed, 92.43 expected, observed/expected ratio (o/e) 0.92, 90% interval 0.77 to 1.1. The upper end of that interval is the gene's LOEUF score, 1.1, which puts it in group 4 of 6, group 1 being the genes least tolerant of losing a copy. Missense variants: 1,301 observed, 1,314.9 expected, observed/expected ratio (o/e) 0.99, 90% interval 0.94 to 1.04. Synonymous variants: 494 observed, 509.84 expected, observed/expected ratio (o/e) 0.97, 90% interval 0.9 to 1.04.
Homologues: Orthologues: chimpanzee NLRP8 (98% identical), macaque NLRP8 (86% identical), dog NLRP8 (59% identical), pig NLRP8 (57% identical), rabbit NLRP8 (56% identical). Paralogues in human: NLRP14 (35% identical), NLRP5 (29% identical), NLRP13 (28% identical), NLRP2 (21% identical), NLRP12 (21% identical), NLRP3 (21% identical), NLRP7 (21% identical), NLRP4 (21% identical), NLRP9 (19% identical), NLRP11 (19% identical), NLRP1 (17% identical), NLRP6 (16% identical), and 8 more.
Diseases named in the same sentence as NLRP8 in open-access papers:
NLRP8 is named in the same sentence as 10 diseases in open-access papers, as found by Europe PMC text mining. Sharing a sentence is not in itself a finding about the gene and the disease. The quoted sentences say what the papers report.
Adult onset (1 paper, 2023). Onset of disease manifestations in adulthood, defined here as at the age of 16 years or later. "Of the four genes harboring rare or low-frequency variants previously identified as associated with adult-onset MS, three (PRF1, NLRP8, and HDAC7) passed quality control and filtering steps to be included in analyses." (PMID 36755464, 2023).
Chronic Obstructive Lung Disease (1 paper, 2019). "NLRP8 rs306481 minor allele genotypes (AG + AA) were more common in the Global Initiative for Chronic Obstructive Lung Disease (GOLD) definition of group A (p = 0.0083)." (PMID 31601004, 2019).
eczema (1 paper, 2018). "Considering we cannot confirm whether the P3 case has an IL25 or NLRP8 variant which could play a role in the absence of eczema or M. contagiosum, it would be difficult to determine whether these variants are playing a role in the proband." (PMID 29556235, 2018).
lung carcinoma (1 paper, 2020). "Function studies were needed to reveal the role of NLRP8 in lung cancer and identify the potential functional variants in these loci." (PMID 32194810, 2020). "Finally, two variants (rs6941653 in OPRM1 and rs402969 in NLRP8) were identified as novel susceptibility loci of lung cancer in Chinese population." (PMID 32194810, 2020). "In this study, NLRP8 expression was found significantly upregulated in lung cancer tissues." (PMID 32194810, 2020).
infection (4 papers, 2019 to 2024). The state of being infected such as from the introduction of a foreign agent such as serum, vaccine, antigenic substance or organism. "Interestingly, T. gondii infection upregulated the expression of NLRC4, NLRP4, NLRP8, NLRP10, NLRP11, NLRP13, and NLRP14 mRNAs at both 4 and 8 h post-infection, but NLRP4, NLRP8, NLRP10, and NLRP11 mRNAs were significantly downregulated at 8 h post-infection compared to that at 4 h post-infection." (PMID 33712075, 2021).
cancer (1 paper, 2020). A tumor composed of atypical neoplastic, often pleomorphic cells that invade other tissues. "However, the functions and roles of NLRP8 in cancers have not been described in the previous study." (PMID 32194810, 2020).
tumor (1 paper, 2020). "Similarly, NLRP8 expression was aberrantly upregulated in tumor tissues (P = 0.015)." (PMID 32194810, 2020).
NLRP8 also shares sentences with these, for which no sentence is quoted: Chagas disease (1 paper); Peri-Implantitis (1); periodontitis (1).